GSK3A (glycogen synthase kinase 3 alpha)
Diseases named in the same sentence as GSK3A in open-access papers (continued):
Sharing a sentence is not in itself a finding about the gene and the disease.
tumor (continued). "Furthermore, palbociclib-insensitive tumours (two-cycles) showed reduced phosphorylation in AKT (p = 0.03) and RSK2 (p = 0.003), as well as the tumour suppressors p38 (p = 0.04) and GSK3a (p = 0.04) and GSK3b (p = 0.004) compared to palbociclib-sensitive tumours (one-cycle)." (PMID 37190140, 2023). "Moreover, GSK3α-mediated tumor angiogenesis relies on HIF1α expression both in vitro and in vivo." (PMID 35292059, 2022). "Moreover, GSK3α-mediated tumor angiogenesis depended on HIF1α expression both in vitro and in vivo." (PMID 35292059, 2022). "Unlike these differences, cell surface PD-1 expression was measured on tumor-infiltrating lymphocytes (TILs) and showed a clear reduction in the double and Gsk3b cKO mouse cells and a lesser reduction in TILs from the Gsk3a cKO mice, consistent with the Pdcd1 gene expression data from the spleen." (PMID 34142056, 2021). "Interestingly, unlike the Akt1−/− and Akt3−/− mice, in which GSK-3 activity is high and does not appear to be inhibited in response to Jenv signaling, Akt2−/− mice possess a high level of basal GSK-3α/β phosphorylation which surprisingly decreases with increased tumor burden." (PMID 24722238, 2014). "Quantitative analysis further disclosed that the decrease in phospho-Akt and phospho-GSK3α/β proteins was particularly marked in tumor cells transduced with the shRNA2 sequence, whereas phospho-Rb expression was more significantly decreased in tumor cells transduced with the shRNA1 sequence." (PMID 24498263, 2014). "The complex in the canonical Wnt pathway formed by β‐catenin includes tumour suppressors axin and APC, as well as two types of Ser‐Thr kinases: CK1α/δ and GSK3α/β." (PMID 41578162, 2026). "Mechanistically, our results suggest that tumor cell-secreted S100A9 binds to RAGE in an autocrine manner and regulates the activation of Akt/GSK3α/β/Snail for increasing cell survival and migration." (PMID 41173834, 2025). "The combination treatment of the Gsk3a inhibitor (SB216763) and the anti-PD-1 antibody significantly inhibited tumor growth and enhanced immune response in a mouse orthotopic tumor model." (PMID 41514551, 2025). "In conclusion, the inhibition of GSK-3α/β and MEK and the microenvironment of tumor initiation mimicked by the CM can convert human normal stem cells into CSCs." (PMID 37181678, 2023). "Consequently, we investigated whether GSK3α regulates tumor angiogenesis." (PMID 35292059, 2022). "Overall, the data suggest that endothelial cells’ paracrine signaling induced TNBC tumor cells to form VM by activating Akt, CREB and Gsk3α among other important factors related to plasticity and angiogenesis." (PMID 35887002, 2022). "Further validation of the cross-talk between GSK3α expression and regulation of the HIF1/VEGFA signaling pathway, both in vivo and in vitro, revealed that GSK3α-mediated cancer tumor angiogenesis was dependent on HIF1α expression in vitro." (PMID 35292059, 2022). "Gsk3b−/− mice suppressed tumor growth to the same degree as Gsk3a/b−/− mice, whereas Gsk3a−/− mice behaved similarly to wild-type, revealing an important role for GSK-3β in regulating T cell-mediated anti-tumor immunity." (PMID 34142056, 2021). "Among highly perturbed gene pairs across multiple tumor types, we noted CXXC1, HSPA5, GSK3A, SERP1, PDIA6, FKBP14, and SCH1, which showed multiple co‐expression changes." (PMID 34698427, 2021). "Our work suggests that GSK3α- and ARIH1-activating agents, as well as EGFR inhibitors, are likely to stimulate anti-tumor immunity and therefore enhance existing cancer therapies by triggering the PD-L1 degradation pathway this work delineates." (PMID 33879767, 2021).
tumor (continued). "In contrast, we observed a reduction of GSK-3α and GSK-3β phosphorylation in tumour tissue with respect to normal tissue, which indicates an activation of these enzymes." (PMID 30410539, 2018). "To identify a representative xenograft model system, we performed western blot analysis of expression of GSK3α/β in aRMS/eRMS cell lines and PDX tumor cultures." (PMID 28968964, 2017). "High GSK3α/β co-expression was seen in aRMS primary tumor culture PCB380 and eRMS primary tumor culture PCB82 in comparison to aRMS cell lines Rh30 and eRMS cell lines RD and Rh18." (PMID 28968964, 2017). "Within the cohort of mice bearing miR-184-overexpressing tumour cells, the expressions of a number of miR-184 targets (e.g., AKT2, GSK3A and S6K2) were reduced in three out of four mice when compared to the control tumours." (PMID 26070602, 2015). "In a separate study phosphorylation of GSK3α/β on the inhibitory site, S21/9, was also found to be increased in NSCLC tumour tissue compared to normal, and this too correlated with poor patient prognosis." (PMID 25486534, 2014). "When comparing kinase activity between patients with or without LNM, we found that the active site of GSK3A (K246) displayed a higher ATP‐binding ability in tumor samples from patient with LNM, consistent with the predicted results from KSEA." (PMID 36520032, 2023). "We found that GSK3A and GSK3B are activated in GAC tumor tissues with lymph node metastasis." (PMID 36520032, 2023). "Here, we demonstrate that GSK-3α rather than GSK-3β is the primary isoform restraining the expression of NKG2D ligands, particularly ULBP2/5/6, on tumor cells, thereby regulating their susceptibility to NK cells." (PMID 33918810, 2021). "Similar to tumor rejection, depletion of Gsk3a alone, unlike Gsk3b, has no direct effect on PD-1 expression, whereas depletion of both together caused the effect to be magnified." (PMID 34142056, 2021). "Notably, while PDA KRASG12D expression does not activate AKT in a cell-autonomous manner, tumor cell AKT substrate phosphosites (e.g., AKTS1 [pT247] and GSK3α [pS21]) are exclusively regulated by stromal PSCs." (PMID 27087446, 2016). "The results showed that the levels of FAK, PYK2, GSK3β, p-GSK3α/βY279/Y216 and β-catenin were all significantly elevated in tumor tissues, with more than 1 score point difference between normal and tumor tissue on average." (PMID 26274564, 2015). "In GSK3α/β KD SW480 cells, reconstitution with WT Flag-GSK3α or Flag-GSK3αY279E but not Flag-GSK3αY279F restored in vivo tumor growth in a cell line xenograft assay." (PMID 26274564, 2015). "Silencing of GSK3α, but not GSK3β resulted in reduced proliferation and enhanced apoptosis in tumor xenografts." (PMID 25714023, 2015). "Likewise, in the lower grade tumor (WDSCC) samples, GSK3α expression was observed in various cellular compartments, including 5 samples that express it in only the NC, 3 samples in the N-CC and 9 samples in the CC." (PMID 25645517, 2015). "The sustained tumor growth inhibition by micellar paclitaxel and 17-AAG was accompanied by marked downregulation of Akt signaling in the tumor tissues, reflected by the reduced levels of p-Akt and p-GSK3α, an immediate downstream substrate of Akt." (PMID 23505544, 2013). "However, the tumor/normal log2 ratios of AXIN1, CREBBP, GSK3A, and NKD2 in the BRAF wildtype samples were low (−0.26 median, 0.12 standard deviation) compared with those in the BRAF mutated samples (−0.02 median, 0.12 standard deviation)." (PMID 23324568, 2013). "Notably, although individual deletion of GSK3α or GSK3β upregulates β-catenin, neither manipulation induces tumor or polyp formation." (PMID 41300341, 2025). "Thus, our study discovered that GSK3A and GSK3B are significantly activated in GAC primary tumor tissues from patients with lymph node metastasis, suggesting GSK3 may serve as a potential therapeutic target which warrants further validations." (PMID 36520032, 2023).
tumor (continued). "SM0014 (AM), whose tumor demonstrated a BRAF fusion, harbored evidence of both MAPK and PI3K pathway activation based on multiple phosphorylation events (BRAF S445, MEK1/2 S217/221, ERK1/2 T202/Y204, GSK3a/b S21/9, p70S6 kinase S371, P70S6 kinase T389, Akt T308)." (PMID 33826614, 2021). "Furthermore, SB induced caspase-3 activation and PARP cleavage only in MiaPaCa2 but not in A549 cells, suggesting that GSK3α/β inhibition selectively induces apoptosis in mutant KRas-dependent tumor cells." (PMID 30514931, 2018). "Importantly, depletion of GSK3α/β inhibited MiaPaCa2 but not A549 tumor growth, further supporting the hypothesis that mutant KRas-dependent but not -independent tumors require GSK3α/β for growth and survival." (PMID 30514931, 2018). "Furthermore, Ctnnb1 expression was increased in tumours compared to both FL and RD livers and among the components of the β-catenin destruction complex, Axin1 and the known β-catenin target Axin2 was significantly upregulated, while Apc, Gsk3a and Gsk3b were not differentially expressed." (PMID 37907668, 2023). "T cell distributions within the peribronchial regions (areas surrounding the tumors rather than within the tumor itself) were also examined revealing accumulations of CD4+ T cells in the double cKO and Gsk3a cKO but not the Gsk3b cKO mice." (PMID 34142056, 2021). "The data from both the EL4 and B16 flank tumors demonstrate non-redundant activity of the GSK-3α and GSK-3β isoforms, with genetic inactivation of GSK-3β resulting in enhanced rejection of both tumor types in the flank." (PMID 34142056, 2021).
cancer (53 papers, 2009 to 2026). A tumor composed of atypical neoplastic, often pleomorphic cells that invade other tissues. "GSK-3α is heavily involved in the regulation of glucose metabolism, which is a hallmark of cancer cells, including HCC." (PMID 39156976, 2024). "It has been reported that 6BIO, a potent inhibitor of GSK-3α/β, has made a promising impact on age-associated diseases such as cancer and neurodegenerative diseases." (PMID 31057395, 2019). "GSK3β outperformed GSK3α as a pan-cancer diagnostic biomarker, achieving superior AUC in 9 tumors." (PMID 41915675, 2026). "GSK3A was recently linked to cancer stem cells and drug resistance." (PMID 40075679, 2025). "Furthermore, we found that GSK3α overexpression could promote proliferation, migration, invasion and colony formation ability of cancer cells, while its loss resulted in an opposite phenomenon." (PMID 35292059, 2022). "We integrated multi-omics data from TCGA, GTEx, and single-cell RNA-seq to analyze GSK3α/β expression patterns in 31 cancers." (PMID 41915675, 2026). "Integrated multi-omics analysis of 31 malignancies revealed divergent dysregulation of GSK3 isoforms: GSK3α was upregulated in 19 solid tumors but suppressed in AML, while GSK3β was elevated in 23 cancers and high-risk AML subtypes (FAB-M0/M1, P = 0.0013)." (PMID 41915675, 2026). "GSK3β plays important roles in the pathogenesis of cancer, while GSK3α has long been considered a functionally redundant protein of GSK3β." (PMID 37031867, 2023). "Due to its role in different cancer entities, GSK3α thus has a pivotal role in regulating the cellular response to amino acid deprivation." (PMID 37686063, 2023). "Collectively, our findings suggest that distinct RPS and RPL proteins play a crucial role in driving dependence toward the GSK3α-dependent proteasomal degradation machinery upon asparagine starvation in cancer cells." (PMID 37686063, 2023). "Particularly since tolerance toward GSK3α inhibition and asparagine deprivation can still develop in these cancer cells." (PMID 37686063, 2023). "GSK3α and GSK3β are distinct isoforms, with GSK3β studied in cancer development while GSK3α was considered redundant." (PMID 37031867, 2023). "The inhibition of GSK3α halts the sourcing of amino acids, which subsequently leads to cancer cell vulnerability toward asparaginase therapy." (PMID 37686063, 2023). "Taken together, these findings provide novel insights into the mechanism of GSK3α action, and are expected to guide future development of therapeutic strategies for cancer treatment." (PMID 35292059, 2022). "For example, GSK3α was found to play a more important role than GSK3β in survival of cancer cells, during resistance to bortezomib-induced cancer treatment." (PMID 35292059, 2022). "The authors also observed that this specific GSK-3α inhibition leads to the reduction in neuroendocrine markers, indicating a possible anti-cancer role for GSK-3α inhibitors." (PMID 34885651, 2021). "This review summarizes the current biological evidence on the role of GSK3α in AD and various types of cancer." (PMID 33339170, 2020). "To follow AKT further downstream, we evaluated the activation of GSK3α/β as AKT substrates offering a potential link to Wnt signaling, which was associated with increased malignancy or resistance formation in cancer cells." (PMID 33287446, 2020). "Investigating the selective inhibition of GSK3α and GSK3β will be critical for elucidating the role that each paralog plays in ND and cancer." (PMID 33339170, 2020). "GSK-3α, a Ser/Thr kinase, was identified as a deactivator of glycogen synthase and a regulator of other cellular functions, like cancer cell survival and proliferation." (PMID 32154227, 2020). "This relevant role of GSK3α inhibition as a target against cancer has been strengthened by other strategies." (PMID 33339170, 2020).
cancer (continued). "It is clear that GSK3α regulates specific cellular functions and has emerged as an attractive target for developing pharmacologic therapies against AD, cancer, and other neurodegenerative disorders." (PMID 33339170, 2020). "Protein level expressions of GSK3α and β-catenin were obtained and we observed that both proteins were consistently downregulated in all the cancer cells treated with lethal concentrations of Lanatoside C." (PMID 31783627, 2019). "Together, these findings suggest that in mutant KRas-dependent human cancer cells, inactivating GSK3α/β induces apoptosis in a β-catenin- and c-Myc-dependent manner." (PMID 30514931, 2018). "A strong inactivation of GSK3α/β has been suggested to support the malignant progression of different types of human cancer." (PMID 29963225, 2018). "GSK3α/β protein expression was observed in the cytoplasmic, nuclear and both the cytoplasmic and nuclear regions of the cancer cells." (PMID 25645517, 2015). "The expression level of pS21GSK3α and pS9GSK3β steadily increased from normal to hyperplasia to benign tumors to carcinomas, indicating that there is an active role of inactive GSK3α/β in OTSCC progression." (PMID 25645517, 2015). "Different roles in diseases have been identified for each isoform: for instance, GSK3β is overexpressed in many types of cancer including ovarian cancer, pancreatic cancer, colon cancer, etc; meanwhile, there are few reports on the role of GSK3α in cancer." (PMID 25010341, 2014). "In cell migration, Tβ4 proteins regulate cancer cell migration under normoxic and hypoxic conditions and by GSK-3α activation." (PMID 25271630, 2014). "However, in our context, the chronic axis is a pertinent aspect to be addressed as the induction of cell death upon GSK3α inhibition in cancer cells involves persistent asparagine depletion." (PMID 37686063, 2023). "However, the clinical significance and specific functions of GSK3α as a kinase in cancer have been largely ignored." (PMID 37031867, 2023). "Notably, the inhibition of GSK-3α kinase function did not stabilize β-catenin in acute myeloid leukaemia cells, providing a feasible strategy to develop paralog-selective GSK-3α inhibitors enforceable to cancer therapy." (PMID 36902175, 2023). "Our finding of ROS production by 2 may add another example of the activation pathway of GSK3α/β responsible for the c-Myc degradation and growth inhibition of cancer cells." (PMID 37547761, 2023). "However, cancer cells can develop tolerance toward GSK3α inhibition and asparagine depletion, whose mechanistic underpinnings are not sufficiently understood." (PMID 37686063, 2023). "We have shown that 2 inhibits mitochondrial complex V and induces mitochondrial dysfunction like oligomycin A. ROS production by the damaged mitochondria activated GSK3α/β, phosphorylating c-Myc for ubiquitin-dependent degradation, which is responsible for the growth inhibition of cancer cells." (PMID 37547761, 2023). "•GSK3α-mediated phosphorylation of THRAP3 at S248 promotes cancer cell migration." (PMID 37031867, 2023). "Thus, we set out to define molecular factors that drive or inhibit cell death upon GSK3α inhibition and asparagine starvation in cancer cells." (PMID 37686063, 2023). "Next, we asked whether GSK3α inhibition mediates cancer cell death in response to asparagine depletion through direct pro-apoptotic signaling." (PMID 37686063, 2023). "GSK3α and GSK3β had specific roles in cell survival, and GSK3α might paly a more important role in cancer cell survival and cancer treatment resistance." (PMID 35292059, 2022). "GSK3α upregulation is equally involved in cancer development and maintenance, where its expression and activity correlate positively with stage development and a poor prognosis in hepatocellular carcinoma, with up to 13-fold overactivity compared to normal cells." (PMID 33339170, 2020).